RN7SL616P (RNA, 7SL, cytoplasmic 616, pseudogene)
Gene: Miscellaneous RNA gene on chromosome 5 (69,478,997 to 69,479,265, reverse strand). Ensembl gene ENSG00000266477.
Homologues: Orthologues: chimpanzee Metazoa_SRP (99% identical), macaque Metazoa_SRP (75% identical), mouse Gm22876 (65% identical). Paralogues in human: RN7SL1 (74% identical), RN7SL2 (74% identical), RN7SL3 (73% identical), RN7SL5P (72% identical), RN7SL559P (71% identical), RN7SL220P (71% identical), RN7SL300P (71% identical), RN7SL678P (71% identical), RN7SL18P (70% identical), RN7SL296P (70% identical), RN7SL304P (70% identical), RN7SL126P (70% identical), and 696 more.